SDC1 (syndecan 1)
Diseases named in the same sentence as SDC1 in open-access papers (continued):
Sharing a sentence is not in itself a finding about the gene and the disease.
glioma (continued). "Our results demonstrate that knockdown of SDC1 expression inhibits glioma proliferation and invasion both in vitro and in vivo." (PMID 28422726, 2017). "Taken together, these results indicate that SDC1 plays a crucial role in the tumorigenesis of glioma." (PMID 28422726, 2017). "We also examined SDC1 expression and evaluated the effects of stable SDC1 knockdown in glioma cell lines." (PMID 28422726, 2017). "Additional studies are needed to further characterize the specific mechanisms by which SDC1 regulates proliferation and invasion in glioma." (PMID 28422726, 2017). "Our results revealed that SDC1 knockdown only weakly inhibited glioma cell growth in MTT assays and at the beginning of the growth curve." (PMID 28422726, 2017). "SDC1 knockdown attenuated proliferation and invasion by glioma cells and markedly decreased PCNA and MMP-9 mRNA and protein expression." (PMID 28422726, 2017). "Glioma patients with SDC1 levels in the top third had dramatically decreased survival compared to those with SDC1 levels in the lowest third (Kaplan–Meier survival analysis, p=0 in both log-rank and Wilcoxon tests)." (PMID 28422726, 2017). "Meanwhile, knockdown of SDC1 expression can inhibits glioma proliferation and invasion through deregulating the c-src/FAK-associated signaling pathway." (PMID 29340066, 2017). "In this study, we examined the functions of SDC1 and its relationship to the integrin-mediated signaling pathway in several human glioma cell lines." (PMID 28422726, 2017). "On the top of that glioma cells secrete high levels of thrombospondin-1, which bind to ανβ3, α3β1 integrins, and SDC-1, participating in carcinoma cell motility and migration." (PMID 24551591, 2014). "Notably, SPP1/HMOX1 and co‐expressed genes were related to activating the PI3K/AKT, JAK–STAT and syndecan 1 pathways in glioma, contributing to the tumour progression of glioma." (PMID 40495644, 2025). "Furthermore, our findings revealed a hallmark of the JAK–STAT signalling pathway (NES = 1.995, p = 0.011, FDR = 0.004) and the syndecan 1 pathway in gliomas expressing HMOX1 (NES = 2.405, p < 0.001, FDR < 0.001)." (PMID 40495644, 2025). "The treatment of U251 glioma cells with emodin significantly decreased mRNA and protein expression levels of NF-KB-regulated expressions of syndecan-1, a surface heparan sulfate that proteoglycan presents in malignant glioma cells but not in normal brain specimens." (PMID 39770078, 2024). "sDC1 may regulate antigen processing and presentation in gliomas through CTSL or CD4, and thus participate in glioma immune escape." (PMID 37088950, 2023). "Further experiments are needed to elucidate the molecular mechanisms of antigen processing and presentation affected by SDC1 in the carcinogenesis of glioma, which may lead to a novel prognostic indicator and more effective treatment strategies." (PMID 35669186, 2022). "Subsequently, we analyzed the module related to both SDC1 and immune infiltration in glioma." (PMID 35669186, 2022). "Our previous studies shown that syndecan-1 (SDC1) may be a novel class of biomarkers for the diagnosis and treatment of glioma, but its specific roles and the in-depth molecular mechanism remain elusive." (PMID 35669186, 2022). "Our study suggests that SDC1 may regulate the activation of T cells by affecting the antigen presentation of glioma cells." (PMID 35669186, 2022). "Subsequently, we analyzed the module related to both SDC1 and immune invasion in glioma." (PMID 35669186, 2022). "In this study, to investigate whether SDC1 affects the immune escape of glioma, we assess the correlation between SDC1 expression and immune scores in three data sets, and the correlation between SDC1 expression and specific immune cells was calculated." (PMID 35669186, 2022). "The DEG analysis between the high and low expression of SDC1 of glioma samples." (PMID 35669186, 2022).
glioma (continued). "The correlation coefficient between SDC1 and immune scores suggests that SDC1 may play a role in regulating immune infiltration in the tumor microenvironment of glioma." (PMID 35669186, 2022). "Moreover, Chandran and colleagues conducted a study to explore extracellular plasma vesicles, and their research showed that Syndecan-1 is a critical biomarker for differentiating low- and high-grade gliomas." (PMID 34722277, 2021). "Two important examples are GPC1 in pancreatic cancer and SDC1 in glioma." (PMID 33494442, 2021). "Together, these results suggest that SDC1 plays a vital role in the angiogenesis of glioma." (PMID 28422726, 2017). "Our current results might therefore support a new mechanism by which SDC1 contributes to the angiogenesis of glioma." (PMID 28422726, 2017). "To confirm that finding, we examined the effects of SDC1 knockdown on glioma cell growth." (PMID 28422726, 2017). "In summary, knockdown of SDC1 expression inhibited the invasive ability of glioma cells." (PMID 28422726, 2017). "Next, we analyzed SDC1 expression in different glioma cell lines." (PMID 28422726, 2017). "In addition, the proliferation and invasion of glioma cell has been attenuated through knockdown SDC1." (PMID 29340066, 2017). "We hypothesize that SDC1 might be transferred from glioma cells to vascular cells via exosomal release and thereby regulate the activation of integrin αvβ3/αvβ5 on vascular endothelial cells." (PMID 28422726, 2017). "Furthermore, SDC1 knockdown inhibited the proliferation and invasion of human glioma cells at least in part by inhibiting integrin-mediated signaling via deregulation of the c-src/FAK-associated signaling pathway." (PMID 28422726, 2017). "Finally, this study provided insights and clues for the next research direction of SDC1 and identified the key pathways and genes that might participate in the immune escape of glioma." (PMID 35669186, 2022). "Generally speaking, Syndecan-1 might regulate the immune infiltration in the TME of glioma." (PMID 35669186, 2022). "Our study elucidated an intricate association between SPP1/HMOX1 and multiple co‐expressed proteins in glioma, highlighting the potential role of SPP1/HMOX1 in regulating cell cycle and growth via the PI3K/AKT, JAK–STAT and syndecan 1 signalling pathways." (PMID 40495644, 2025). "SPP1/HMOX1 was involved in influencing glioma cell motility through the PI3K/AKT, JAK–STAT and syndecan 1 signalling pathways." (PMID 40495644, 2025). "Finally, functional experiments were performed to evaluate the roles of risk genes in the cell viability of glioma cells, which demonstrated that silencing BGN, SDC1, SERPINA1, TUBA1C, C1GALT1C1L and SPTBN5 could inhibit the growth and viability of glioma cells." (PMID 38396140, 2024). "Among the plasma-derived EV proteins, the authors identified syndecan 1 (SDC1) as a valid biomarker able to discriminate between GBMs and low-grade glioma." (PMID 39337267, 2024). "Moreover, functional experiments were performed to evaluate the roles of risk genes in the cell viability and cell number of glioma U87 and U251 cells, which demonstrated that silencing BGN, SDC1, SERPINA1, TUBA1C, C1GALT1C1L and SPTBN5 could inhibit the growth and viability of glioma cells." (PMID 38396140, 2024). "In this study, we aimed to understand the relationship among SDC1, TGM2, FLOT1 and BHMT in modulating glioma autophagy and investigated their roles in regulating the radiosensitivity of glioblastoma by affecting the fusion of autophagosomes and lysosomes." (PMID 37441590, 2023). "In this study, we found that heparan sulfate proteoglycan 2 (perlecan) (HSPG2), syndecan-1 (SCD1), clathrin (CLTC), and dynamin (DNM1) were present in all patient-derived glioma cells." (PMID 36992317, 2023). "More interestingly, the Gliovis database showed that FLOT1 was positively correlated with SDC1 expression and BHMT was positively correlated with TGM2 expression in glioma tissues." (PMID 37441590, 2023).
glioma (continued). "To explore the correlation of SDC1 expression with immune infiltration, we first used the ESTIMATE algorithm to assessed glioma purity as well as stromal and immune scores." (PMID 35669186, 2022). "In glioma cells, YKL‐40 promotes the formation of the bond between SDC1 and αvβ5 and further activates the ERK1/2 pathway through FAK397, thereby increasing the expression of VEGF and promoting angiogenesis." (PMID 34110111, 2021). "Results for both the TCGA and GSE4290 datasets indicated that elevated SDC1 expression is closely associated with increased progression in glioma tumors; the comparatively low malignancy of Grade II glioma might partially explain the lack of an increase in SDC1 expression in that stage." (PMID 28422726, 2017). "However, the specific mechanisms by which SDC1 promotes glioma remain unknown." (PMID 28422726, 2017). "However, the mechanism by which SDC1 knockdown inhibits angiogenesis in glioma remains unknown." (PMID 28422726, 2017). "These bioinformatics analyses imply that the high level of SDC1 and TGM2 is a key factor of tumor radioresistance and may affect the outcome of radiotherapy of glioma patients." (PMID 37441590, 2023). "For example, EVs isolated from the plasma of patients with high-grade gliomas, analyzed with the tandem mass tag labeling LC-MS/MS method, showed high levels of syndecan-1 (SDC1), which can discriminate between high-grade glioblastoma multiforme and low-grade glioma." (PMID 36005596, 2022). "Recently, we identified the surface protein syndecan 1 (SDC1) in tumor-derived EVs, and plasma levels of EV-SDC1 could discriminate between GBM and low-grade glioma." (PMID 35217608, 2022). "It suggests that SDC1 may have a positive correlation with activated CD4+T and CD8+T cells in the TME of glioma." (PMID 35669186, 2022). "Protein–protein network interaction analysis showed that SDC1 may regulate antigen processing and presentation through CTSL or CD4 in glioma." (PMID 35669186, 2022). "Indeed, the PEA technology has been applied for analysing protein cargo of EVs from different body fluids and to reveal prognostic BMs of glioma and glioblastoma cancer patients in plasma, for example syndecan‐1 (SYND‐1 also known as SDC1)." (PMID 35838333, 2022). "We found that IL-8 is mainly expressed by macrophages in TME rather than glioma cells, and its receptor, SDC1, is highly expressed in CSCs." (PMID 31118022, 2019). "SDC1 in plEVs could discriminate between GBM and low-grade glioma with a sensitivity of 71%, and specificity of 91%.The findings support the concept of circulating plEVs as a tool for non-invasive diagnosis and monitoring of gliomas." (PMID 40867329, 2025). "Interestingly, the clinical data in TCGA showed that glioma patients with elevated SDC1 expression did not survive as long as patients with lower SDC1 expression." (PMID 28422726, 2017). "Unlike our previous study showing syndecan 1 to be the main VAR2CSA receptor in the placental syncytium, we found several interesting hits on the glioma cell lines, including syndicans, glypicans, neuropilins, decorin, versican, CSPG4, and PTPRZ1." (PMID 31466397, 2019).
ovarian carcinoma (31 papers, 2007 to 2025). A malignant neoplasm originating from the surface ovarian epithelium. "Using the antibody scFv 46F2 to inhibit the tubule-like structures of ovarian cancer VM-associated cells, we established the prominent role of SDC1 in VM, although B-FN was able to induce in vitro VM formation." (PMID 31443604, 2019). "We observed that ovarian cancer VM-associated cells were able to secrete SDC1 and B-FN and expressed the stem cell markers CD44 and EpCAM." (PMID 31443604, 2019). "In contrast, for periostin, loss of both Syndecan-1 and Syndecan-4 negatively affects ovarian cancer cell adhesion, which supports the notion that periostin utilizes a distinct mode of cellular interaction." (PMID 22640878, 2012). "Similarly, COL4A1 and SDC1 expression levels have previously been linked to a dismal prognosis among patients with ovarian cancer." (PMID 37488671, 2023). "Therefore, Syndecan-1 and −4 expression is dispensable for adhesion of ovarian cancer cells to rTGFBI, however, the loss of Syndecan-1 expression can synergize with the loss of ß1 integrin expression to stimulate rTGFBI adhesion." (PMID 22640878, 2012). "Sdc1 and E-cad have been associated with epithelial-mesenchymal transition, and it has recently been shown that ET-1 mediated signalling is required during epithelial-mesenchymal transition in ovarian cancer progression." (PMID 17244359, 2007). "In previous articles it has been reported that the expression of shed SDC1 was a poor prognostic factor of overall survival in patients with ovarian cancer and a marker for the progression of EOC." (PMID 31443604, 2019). "We also investigate a possible employment of L19-IL2, an immunocytokine specific for B-FN, and anti-SDC1 46F2SIP (small immuno protein) antibody in combination therapy in a human ovarian carcinoma model." (PMID 31443604, 2019). "Patients with advanced ovarian cancer exhibit significantly lower epithelial SDC1 expression and significantly higher stromal SDC1 expression in reciprocal pattern compared to normal controls." (PMID 26293675, 2015). "OC-46F2 was found to inhibit SDC1 distribution in the tumor milieu, thus preventing vascular maturation and tumor growth in experimental human melanoma and ovarian carcinoma models." (PMID 26293675, 2015). "Increased syndecan-1 staining was a poor prognostic factor for survival also in ovarian cancer, where syndecan-1 was also present in the stromal compartment." (PMID 26420915, 2015). "Moreover, the expression of shed SDC1 is a poor prognostic factor of overall survival in patients with ovarian cancer." (PMID 31443604, 2019). "Finally, in ovarian cancer, enhanced expression of syndecan-1 promotes metastasis by activating mitogen-activated protein kinase, ERK, and phosphatidylinositol (PI)-3 kinase/AKT signaling." (PMID 30135409, 2018). "In addition, the expression of stromal SDC1 was a poor prognostic factor of overall survival in patients with ovarian cancer." (PMID 26293675, 2015). "We observed that in a human ovarian carcinoma model the combined treatment using L19-IL2 and the new anti syndecan-1 46F2SIP antibody format was effective in modulation of epithelial-mesenchymal transition (EMT) markers, loss of stemness properties of tumor cells and alleviated hypoxia." (PMID 31443604, 2019). "In a comparative study of SDC1 and B-FN expression in ovarian cancer tissues, we observed that some vessels negative for CD31 and anti-B-FN were positive for the anti-syndecan-1 antibody." (PMID 31443604, 2019). "It is important to note that although Syndecan-1 expression is absent in the normal ovary, it is upregulated in ovarian cancer as well as in tumor stroma." (PMID 22640878, 2012). "These preliminary observations and the high SDC1 and B-FN levels dosed in ascite from EOC patients afforded the possibility to investigate the effectiveness of a combined therapy using anti-SDC1 46F2SIP antibody and immunocytokine L19-IL2 in a human ovarian carcinoma model." (PMID 31443604, 2019).
ovarian carcinoma (continued). "Thus, for ovarian cancer cells, it appears neither Syndecan-1 nor Syndecan-4 is necessary for adhesion to TGFBI, nor does the loss of Syndecan-4 synergize with αvß3 to stimulate adhesion to TGFBI." (PMID 22640878, 2012). "In this study, we show that both SDC1 and B-FN are involved in EOC progression and we hypothesize a possible employment of L19-IL2 and of the new anti-syndecan-1 46F2SIP (small immuno protein) antibody format in combined therapy to treat a human ovarian carcinoma model." (PMID 31443604, 2019). "However, the expression of CDC20, SDC1 and ALDH1A1 were not significantly correlated with PFS of ovarian cancer patients (all P>0.05)." (PMID 33123295, 2020).
lupus (28 papers, 2008 to 2025). "Other reports indicated pathogenic roles for syndecan-1 in hematopoietic diseases; syndecan-1 surface expression was predictive of T-cell autoactivation in a murine lupus model." (PMID 38912739, 2024). "Syndecan-1 expression level on GC B cells is associated with Tfh cell expansion and disease progression in lupus-prone mouse strains." (PMID 28045014, 2017). "Therefore, we wondered whether syndecan-1 was associated with the regulation of Tfh cells in lupus-prone mice." (PMID 28045014, 2017). "Expansion of TCRβ+ T cells expressing syndecan-1 (CD138) correlated with disease severity in lupus-prone MRL/Lpr mice." (PMID 40943300, 2025). "In lupus-prone mice, syndecan-1 has been shown to interact with death receptor 6, an orphan immune regulator, which regulates expansion and activation of autoreactive follicular helper T cells and disease progression." (PMID 37854589, 2023). "In the same study, 111 patients with systemic lupus erythematosus had median syndecan-1 levels of 34.2 (20.9–50.0) ng/ml, and the levels were related to disease activity and lupus nephritis." (PMID 34242246, 2021). "In both cohorts of lupus biopsy samples, we found that SDC1 was expressed by a few infiltrating plasma cells, but the vast majority of stained cells were renal tubular cells." (PMID 30065042, 2018). "Taken together, in the current study, we identified a novel regulatory mechanism that depends on the interaction of DR6 with syndecan-1 for preventing expansion and activation of Tfh cells and disease progression in lupus-prone mice." (PMID 28045014, 2017). "Here the authors show that the orphan receptor DR6 is a Tfh cell marker that binds syndecan-1 on GC B cells driving autoimmunity in lupus-prone mice." (PMID 28045014, 2017). "We first analyzed the percentage of plasma cells, identified according to their expression of CD138 (syndecan-1), in the spleen and in the blood of 32–36 week-old proteinuria-positive lupus NZB/W mice and control age-matched BALB/c mice." (PMID 23520491, 2013). "In another lupus-prone mouse strain, NZB mice, the GC cells (cyan) also expressed syndecan-1 (green)." (PMID 28045014, 2017). "Importantly, we identify syndecan-1 as a binding partner for DR6, and we clarify whether and how this dysregulated DR6/syndecan-1 interaction leads to autoimmunity in lupus-prone mice." (PMID 28045014, 2017). "The levels of syndecan-1 expression of GL7− CD19+ non-GC B cells were low and comparable between lupus-prone and healthy B6 mice, although CD19 expression level was comparable among these cells." (PMID 28045014, 2017).
plasmacytoma (28 papers, 2004 to 2026). Plasmacytoma is a localized mass of neoplastic monoclonal plasma cells that represents approximately 5% of all plasma cell neoplasms. "The cell surface heparan sulfate proteoglycan CD138 (also known as syndecan-1) has been utilized in the diagnosis of plasmacytoma as a specific and sensitive marker of bone marrow and circulating blood malignant plasmacytes." (PMID 23407614, 2013).